USP7 (ubiquitin specific peptidase 7)
Diseases named in the same sentence as USP7 in open-access papers (continued):
Sharing a sentence is not in itself a finding about the gene and the disease.
lung adenocarcinoma (12 papers, 2015 to 2024). A carcinoma that arises from the lung and is characterized by the presence of malignant glandular epithelial cells. "To further investigate the role of USP7 in the immune microenvironment of human lung adenocarcinoma (LUAD), we analyzed the results of transcriptome sequencing for 517 patients with LUAD in TCGA database." (PMID 32802195, 2020). "The TGCA database was used to assess the role of USP7 in the immune microenvironment of human lung adenocarcinoma (LUAD)." (PMID 32802195, 2020). "Moreover, significantly higher levels of USP7 were found in colonic and lung adenocarcinomas as well as thyroid carcinoma when compared to their paired peritumoral tissues." (PMID 37081042, 2023). "The results showed that USP7 was not only highly expressed in brain metastases of the commonly used murine Lewis tumor model but also in human primary lung adenocarcinoma (A07, B09, G01) and brain metastases (F03, H09, G11), indicating that USP7 is a potential target for the treatment of BRM." (PMID 36698296, 2023). "Moreover, it has been reported that USP7 reduction is related to chemo- and radio- therapy resistance in lung adenocarcinomas." (PMID 25885523, 2015). "In lung adenocarcinoma, MYH9 stabilizes c-Myc via deubiquitination with the help of the deubiquitinating enzyme ubiquitin-specific peptidase 7 (USP7) to promote cell cycle progression and EMT signaling." (PMID 39273383, 2024). "Additionally, USP7 could regulate lung adenocarcinoma through USP7/Raf‐1/ERK1/2 axis." (PMID 39107958, 2024). "In summary, our results indicate that USP7 deubiquitinates Raf-1 and is a new regulator of the ERK1/2 signaling pathway in lung adenocarcinoma." (PMID 35948545, 2022).
Intellectual disability (10 papers, 2017 to 2025). "USP7 mutations result in similar phenotypes that include intellectual disability, autism spectrum disorder, epilepsy, and hypogonadism." (PMID 40166258, 2025). "We found one protein named USP7 satisfying these criteria, where individuals carrying gene mutations exhibited developmental delay, intellectual disability, and hypogonadism in both sexes." (PMID 38517962, 2024). "Previous studies have found that children carrying USP7 mutations and deletions may be associated with neurodevelopmental disorders such as autism spectrum disorders, intellectual disabilities and speech/movement disorders." (PMID 41368944, 2025).
acute myeloid leukemia (9 papers, 2018 to 2025). Acute myeloid leukemia (AML) is a group of neoplasms arising from precursor cells committed to the myeloid cell-line differentiation. "In physiological aging as in Myelodysplastic Syndrome (MDS) and Acute Myeloid Leukaemia (AML), DUBs, including USP7, USP15, and A20, exhibit either increased or decreased expression." (PMID 39108012, 2024). "Furthermore, the transcriptional regulator 1 (ASXL1), which is essential for myeloid differentiation, is stabilized by USP7 in acute myeloid leukemia (AML)." (PMID 33327527, 2020). "Similarly, in acute myelogenous leukemia (AML), nucleophosmin 1 (NPM1) regulates PTEN nuclear exclusion by inhibiting its USP7-mediated deubiquitination." (PMID 41157055, 2025).
autism spectrum disorder (9 papers, 2017 to 2025). A spectrum of developmental disorders that includes autism, and Asperger syndrome. "The USP7 gene, implicated in autism spectrum disorders, has been investigated in mouse models to comprehend its involvement in neurodevelopment." (PMID 39135741, 2024). "Mouse models have been crucial in unraveling the intricate roles of TRIP12 and USP7 genes in neurodevelopment and embryogenesis, shedding light on their potential implications in various biological conditions, particularly autism spectrum disorders in the case of USP7." (PMID 39135741, 2024).
chronic lymphocytic leukemia (9 papers, 2017 to 2025). "In chronic lymphocytic leukemia (CLL), USP7 is overexpressed and interferes with HR pathways, leading to an accumulation of unrepaired DSBs." (PMID 38702734, 2024). "Likewise, USP7 inhibitor, P5091, regains PTEN nuclear pool and restores its tumor suppressive functions in chronic lymphocytic leukemia (CLL)." (PMID 31114498, 2019).
nasopharyngeal carcinoma (9 papers, 2009 to 2026). A carcinoma arising from the nasopharyngeal epithelium. "In order to investigate the potential role of USP7 in regulating PML-NBs, we treated the EBV-negative nasopharyngeal carcinoma cell line, CNE2, with siRNA for USP7 (siUSP7) or control siRNA for GFP (siGFP)." (PMID 21305000, 2011). "Silencing of USP7 was found to increase the number of PML-NBs, to increase the levels of PML protein and to inhibit PML polyubiquitylation in nasopharyngeal carcinoma cells." (PMID 21305000, 2011). "Additionally, EBV EBNA1 hijacks the host kinase CK2 and the deubiquitinase USP7 to disrupt PML NBs, contributing to nasopharyngeal carcinoma." (PMID 39823515, 2025).
developmental delay (8 papers, 2018 to 2025). "Variants in USP7 cause a neurodevelopmental disorder with developmental delay, behavioral, hypotonia, seizures, hypogonadism (MIM# 616,863)." (PMID 36538041, 2023). "P3 presents mild motor developmental delay, absent speech, behavioral anomalies and ASD, suggesting that USP7 haploinsufficiency should be suspected in a case of ASD with absence of speech and behavioral disorders." (PMID 33050239, 2020).
lung squamous cell carcinoma (8 papers, 2015 to 2025). "Overall, we have demonstrated that lung squamous cell carcinoma and large cell carcinoma overexpressed USP7, and high levels of USP7 play an important role in tumor invasion and metastasis in squamous cell carcinoma and large cell carcinoma." (PMID 25519684, 2015). "For example, USP1 deubiquitinates FANCD2/FANCI or PCNA to prevent the recruitment of interstrand crosslink repair proteins and translesion DNA polymerase to inhibit DNA repair; USP7 regulates lung squamous cell carcinoma cell proliferation through MEK/ERK signaling by deubiquitinates the Raf-1." (PMID 37107644, 2023). "USP7 is a novel marker for predicting the prognosis of patients with lung squamous cell carcinoma and large cell carcinoma, and may serve as a potential therapeutic target." (PMID 25519684, 2015). "Thus, USP7 might be used as a prognostic factor and therapeutic target in treating lung squamous cell carcinomas and large cell carcinoma." (PMID 25519684, 2015). "Here, our results indicate that lung squamous cell carcinoma and large cell carcinoma tumors and NSCLC cell lines express high levels of USP7 compared with corresponding non-tumorous tissues or immortalized normal lung cell lines." (PMID 25519684, 2015).
osteoporosis (8 papers, 2017 to 2025). A condition of reduced bone mass, with decreased cortical thickness and a decrease in the number and size of the trabeculae of cancellous bone (but normal chemical composition), resulting in increased fracture incidence. "Since HBX 41,108 has been reported as a potential anticancer drug, our findings present the point that application of USP7 inhibitors may impair osteogenic ability and cause related side effects such as osteoporosis during antineoplastic therapy." (PMID 28807012, 2017). "BMSC-derived extracellular vesicles alleviate mouse osteoporosis via USP7-mediated YAP1 stability and Wnt/β-catenin pathway modulation." (PMID 38399333, 2024). "The abnormal decrease in USP7 expression found in osteoporosis further supports its critical role in the pathogenesis of bone-related diseases." (PMID 37199589, 2023). "In this study, we found that USP7 enhanced the stability of KDM6B to promote KDM6B expression inhibited the ubiquitination, while miR‐15b inhibits USP7 expression in osteoporosis." (PMID 33434305, 2021). "Taken altogether, miR‐15b inhibits osteoblast differentiation and autophagy to aggravate osteoporosis by targeting USP7 to regulate KDM6B expression." (PMID 33434305, 2021). "We established osteoporosis models through ovariectomy and determined that miR‐15b was highly expressed whereas USP7 and KDM6B were poorly expressed in tissue of osteoporosis mice." (PMID 33434305, 2021). "Of note, our data revealed that inhibition of proteasome up‐regulated expression of USP7 and KDM6B, while increased USP7 expression promoted osteoblast differentiation and autophagy, alleviating osteoporosis." (PMID 33434305, 2021). "Additionally, in ovariectomy (OVX) mice, USP7 levels are lower than those in sham-operated mice, suggesting that USP7 plays a role in osteoporosis." (PMID 37199589, 2023). "In summary, these results indicate that in osteoporosis USP7 expression is altered in osteoclast lineage cells, which might contribute to the disease phenotype." (PMID 37199589, 2023). "Moreover, P5091, a USP7 inhibitor, accelerates osteoclast formation and bone resorption, suggesting that the side effects of osteoporosis should be considered while using this compound in anticancer therapy." (PMID 37199589, 2023). "In conclusion, our study demonstrated that up‐regulation of miR‐15b could inhibit the expression of USP7, which potentially suppress the osteoblast proliferation, differentiation and autophagy to aggravate osteoporosis through inhibition of KDM6B expression." (PMID 33434305, 2021). "Thus, it can be concluded that miR‐15b overexpression suppressed osteoblast differentiation and autophagy to aggravate osteoporosis by suppressing USP7/KDM6B axis." (PMID 33434305, 2021). "Moreover, USP7 might contribute to osteoporosis, which enhanced osteoclast differentiation by deubiquitinating HMGB1." (PMID 40329406, 2025). "Therefore, the obtained data suggested that USP7 could induce osteoblast differentiation and autophagy to ameliorate osteoporosis by increasing KDM6B expression." (PMID 33434305, 2021). "In accordance, the analyzed cancellous bone of the femoral head from patients with osteoporosis (BMD, T<-2.5) also showed decreased Usp7 expression." (PMID 37199589, 2023). "However, the effects of miR‐15b regulating KDM6B by targeting USP7 on osteoporosis remain unclear." (PMID 33434305, 2021). "To identify the in vivo interaction among miR‐15b, USP7 and KDM5B, we established models of osteoporosis mice and treated them with injection of miR‐15b agomir + oe‐NC, agomir‐NC + oe‐NC and miR‐15b agomir + oe‐KDM6B." (PMID 33434305, 2021). "Additionally, USP7 stabilizes KDM6B and YAP1, counteracting osteoporosis and facilitating osteogenic differentiation through both Wnt/β-catenin and Hippo pathways." (PMID 40427572, 2025).
osteoporosis (continued). "In addition, more studies are required in order to adequately define the detailed mechanisms by which miR‐15b interacts with USP7 and KDM6B and influences osteoporosis progression." (PMID 33434305, 2021). "Additionally, gene therapy approaches targeting key regulatory enzymes like USP7 and USP10 could offer novel therapeutic strategies for osteoporosis." (PMID 40427572, 2025).
acute lymphoblastic leukemia (7 papers, 2018 to 2022). Leukemia with an acute onset, characterized by the presence of lymphoblasts in the bone marrow and the peripheral blood. "Hematoxylin and eosin (H&E) staining indicated that the USP7-depleted mice had less infiltration of lymphoblastic leukemia cells into the spleen in comparison with the control mice." (PMID 30370059, 2018). "We applied our application to analyze RNA-seq data generated from a USP7 knockdown in T-cell acute lymphoblastic leukemia (T-ALL) cell line, which identified upregulated expression of a TAL1-associated proliferative signature in T-cell acute lymphoblastic leukemia cell lines." (PMID 35205126, 2022). "In acute lymphoblastic leukemia, NOTCH1 contributes to the upregulation of USP7 levels, and USP7, in turn, influences the stability of NOTCH1, which possibly forms a positive-feedback interaction between the two proteins." (PMID 34869041, 2021). "Inhibiting the protein ubiquitin-specific protease 7 (USP-7) may offer a treatment option for patients with T-cell acute lymphoblastic leukemia (T-ALL), an incurable and aggressive cancer." (PMID 30370059, 2018).
pancreatic cancer (7 papers, 2016 to 2026). "USP7 is an oncogene in pancreatic cancer, and USP7 inhibition blocks PDAC development and promotes cell death in vitro and in vivo." (PMID 37605223, 2023). "UHRF1, an USP7 substrate, has been observed in many cancer tissues such as breast, bladder, kidney, lung, prostate, cervical and pancreatic cancers." (PMID 27780924, 2016). "Therefore, our results indicated that the USP7/FBP1 axis modulated the sensitivity of pancreatic cancer to PARP inhibitors." (PMID 34854226, 2022). "Moreover, the subsequent co‐IP assay demonstrated that USP7 interacted with FBP1 reciprocally in pancreatic cancer cells." (PMID 34854226, 2022). "We therefore suggest that USP7 inhibitors in combination with PARP inhibitors might manifest more powerful antitumor effects than PARP inhibitors alone in pancreatic cancer cells." (PMID 34854226, 2022). "In pancreatic cancer cells, USP7 regulation of DNMT1 stability is dependent on DNMT1 acetylation." (PMID 34572918, 2021). "Collectively, our results identify a novel USP7–FBP1–DNMT1 signaling axis in pancreatic cancer, which might indicate that USP7 inhibitors and PARP inhibitors might have more powerful antitumor effects than PARP inhibitors alone in pancreatic cancer patients." (PMID 34854226, 2022). "As USP7 is responsible for the subcellular distribution of FBP1 but does not influence the stability of FBP1 in pancreatic cancer cells, we were curious about how USP7 regulates this process." (PMID 34854226, 2022).
bladder cancer (6 papers, 2019 to 2025). "USP7 (ubiquitin-specific protease 7), also named as HAUSP (herpesvirus-associated protease), has been discovered to be associated with oncogenesis in some cancer types, including bladder cancer." (PMID 37215134, 2023). "In bladder cancer cells with HR defects caused by CCDC6 depletion (native or induced upon USP7 inhibitor addition) we observed that RRx-001, by exposing cancer cells to reactive oxygen species, enhanced the sensitivity to PARP-inhibitor drugs, as supported by the DRI value (DRI > 1)." (PMID 30786932, 2019). "The J82, T24, 5637 and KU-19-19 bladder cancer cells were exposed to USP7 inhibitor P5091 in presence of cycloheximide to analyse the CCDC6 stability." (PMID 30786932, 2019). "It is necessary to determine whether these USP7 inhibitors can improve immunotherapy in bladder cancer." (PMID 37215134, 2023). "It is required to explore whether USP7 inhibitors could enhance the immune response of bladder cancer." (PMID 37215134, 2023). "USP7 has been reported to modulate CCDC6 levels in bladder cancer and lung neuroendocrine cancers." (PMID 37497216, 2023). "It has been reported that USP7 modulated the expression levels of CCDC6 in bladder cancer." (PMID 37215134, 2023). "Therefore, it is essential to investigate the role of USP7 in bladder cancer." (PMID 37497216, 2023). "In accordance, a positive correlation between USP7 and KDM4A protein expression was noted in bladder cancer clinical samples." (PMID 41429764, 2025). "Functional validation tests confirmed that USP7 and KDM4A act complementarily to drive bladder cancer cell proliferation." (PMID 41429764, 2025). "In a recent study, P5091, an inhibitor of USP7, promoted CCDC6 degradation and sensitized bladder cancer cells to the cytotoxic effect of the PARP-inhibitor olaparib." (PMID 37497216, 2023). "Treatment with USP7 inhibitor determined a significant decrease of the GFP positive cells, compared to non-treated cells, suggesting that the reduction of CCDC6 levels affected the DNA repair by HR in bladder cancer cells." (PMID 30786932, 2019). "So, out of 46 bladder cancer tumor samples, we could identify a sub-group of high grade bladder cancers with a low expression of CCDC6 and a moderate expression of USP7 (cluster 1), and a sub-group of high grade tumors with higher expression of both the proteins (cluster 3)." (PMID 30786932, 2019).
brain tumor (6 papers, 2018 to 2026). "This establishes the critical role of USP7 in brain tumor development and suggests the therapeutic potential of USP7 inhibitors for treating GBM." (PMID 41818193, 2026). "We first show that antigen processing and presentation by HLA class I (HLA-I) is the top enriched immune response pathway in the global proteome of aggressive paediatric USP7-ATRT brain tumour cells following ZIKV infection." (PMID 41166287, 2025). "We first investigated whether ZIKV infection moderates innate or adaptive immune responses within the aggressive paediatric brain tumour cell line USP7-ATRT." (PMID 41166287, 2025). "Here, we identify 19 HLA-I ZIKV peptides presented on the surface of USP7-ATRT brain tumour cells." (PMID 41166287, 2025). "Notably, re-expression of wild-type, but not C223S mutant, USP7 restored MGMT protein levels in USP7-depleted T98G cells, linking USP7 catalytic activity to MGMT stabilization in brain tumor cells." (PMID 40835840, 2025). "None of the recombinant TNF proteins were cytotoxic, and TNF-alpha significantly increased both USP7 and USP13 confluence, indicating that soluble TNF-alpha enhances brain tumour cell growth." (PMID 40240536, 2025). "To investigate this, we infected and performed RNA-Seq on USP7 (P7) and USP13 (P13) brain tumour cells for 12, 18, and 24 h." (PMID 40240536, 2025). "Interestingly, we found that the clusters containing the majority of the pediatric brain tumors (Clusters 2/3, 4, and 5; α, ß, and Γ respectively) had significant differences in the expression patterns of LSD1, REST, and USP7." (PMID 30227871, 2018). "Multiple cell cycle, DNA replication and DNA repair terms are significantly upregulated specifically in USP13 cells during 12–18 hpi, whereas cell cycle-related terms are significantly downregulated in USP7 at 24 hpi; indicating that ZIKV may differentially regulate brain tumour cell growth." (PMID 40240536, 2025).
chronic myelogenous leukemia (6 papers, 2018 to 2025). "In chronic myeloid leukaemia (CML), BCR-ABL can enhance USP7-induced deubiquitination of PTEN, which is conducive to nuclear rejection." (PMID 36969062, 2023). "In chronic myelogenous leukemia (CML), USP7 is required for stabilization of BCR-ABL and activation of BCR-ABL signaling.Inhibiting USP7 was shown to cause BCR-ABL destabilization and to trigger apoptotic signaling pathways." (PMID 34869041, 2021).